APP (amyloid beta precursor protein)
Diseases named in the same sentence as APP in open-access papers (continued):
Sharing a sentence is not in itself a finding about the gene and the disease.
Alzheimer disease (continued). "However, when poly(I:C) was injected intraperitoneally into the APP/PS1 mouse model of Alzheimer’s disease (AD), activation of TLR3 attenuated neuronal loss and inhibited the activation of microglia and astrocytes, decreasing the expression of proinflammatory mediators in the hippocampus." (PMID 37124206, 2023). "The initial target for the first GSI, however, was Alzheimer’s disease (AD), in which the γ-secretase complex is associated with the deposition of senile plaques, resulting from the aberrant deposition of amyloid precursor protein (APP) and the production of short amyloid-β peptides (Aβ)." (PMID 37760535, 2023). "Finally, proximity ligation assays were used to quantify NMDA-PrPC complex formation in neuronal primary cultures isolated from APPSw/Ind transgenic mice, an Alzheimer’s disease model expressing the Indiana and Swedish mutated version of the human amyloid precursor protein (APP)." (PMID 36672218, 2023). "Altogether, our findings of the commonality of APOEε4 and APP/PS1 mutation effect on hippocampus-PCC structural connectivity indicate that the disrupted white matter integrity of hippocampus-PCC tract is a promising imaging marker for preclinical Alzheimer’s disease, either familial or sporadic." (PMID 36850008, 2023). "SORL1 mutations, occurring frequently in a subset of familial cases of Alzheimer’s disease (AD), have been documented, but their pathogenic potential is not yet clear and questions remain concerning their putative influence on the physiopathological processing of APP." (PMID 38132122, 2023). "Also, L1 binds to Aβ and reduces Alzheimer’s disease pathology in mice when full-length L1-encoding adeno-associated virus is injected into the hippocampus and occipital cortex of AD mice expressing a mutant APP gene." (PMID 35013124, 2022). "Also, it has been reported that 3′UTR polymorphisms of amyloid precursor protein (APP) (APP-118C/A and APP-534G/A) may affect the binding affinity of miR-153 and the regulation of APP expression by this miRNA in Alzheimer’s disease." (PMID 36158686, 2022). "Overexpression of the gene APP is implicated in the “amyloid cascade”, related to the pathogenesis of Alzheimer disease (AD) affecting approximately 20% of persons with DS beyond 40 years of age, 40% beyond 50 years, 80% and more beyond 60 years." (PMID 33709029, 2021). "Several transgenic mouse models have been generated that overexpress APP with or without familial Alzheimer disease (FAD) mutations or combinations of human mutant APP, PS, and tau transgenes that reflect certain aspects of human AD." (PMID 32727580, 2020). "Notably, it also increases APP processing and extends the lifespan of terminally-sick mice with neurodegenerative disease, suggesting that M1 PAMs have the potential to improve cognition and to modify the underlying cause of Alzheimer's disease." (PMID 33584282, 2020). "Interestingly, that by creating an amyloid cascade hypothesis, D. Hardy assumed that “The mutations in APP so far described are responsible only for a small proportion of cases of Alzheimer’s disease." (PMID 31940879, 2020). "Taken together, all of these results may indicate miR-338-5p as an innovative modulator in the pathogenesis of Alzheimer’s disease, and also suggest that the protective effect of miR-338-5p on neuronal apoptosis may underlie its beneficial effect on APP/PS1 mice." (PMID 33087587, 2020). "In fact, missense mutations in the APP gene were first reported to cause early-onset familial Alzheimer’s disease (EOFAD)." (PMID 32235595, 2020). "This is relevant to Alzheimer’s disease because classic theory describes histopathological alterations caused by senile plaques, with neurofibrillary tangles and neuronal losses that are secondary to the deposition of β-amyloid substances due to altered metabolism of amyloid precursor protein (APP)." (PMID 31052367, 2019).
Alzheimer disease (continued). "Extra copy of chromosome 21 and, more importantly, APP gene with increased β-amyloid peptide production are probable mechanisms for the universal development of Alzheimer’s disease neuropathology and high risk of Alzheimer’s disease-like dementia in Down syndrome." (PMID 31109140, 2019). "Interestingly, human β2 can be sequentially cleaved by secretases; cleavage of β2 takes place analogously to the processing of the amyloid precursor protein (APP), whose amyloidogenic cleavage is cause and aggravation of the pathogenesis in Alzheimer’s disease." (PMID 31614896, 2019). "Alzheimer’s disease is a progressive neurodegenerative disease and the most common cause of dementia, where the accumulation and deposition of amyloid-β (Aβ) peptides cleaved from amyloid precursor protein (APP) in the brain trigger the pathogenic cascade of the disease." (PMID 29401741, 2018). "Since APP and the PSENs are linked in their common involvement in Aβ production, an alternative hypothesis for Alzheimer’s disease pathogenesis requires that a convincing alternative explanation is given for the relationship between the functions of APP and PSENs, and EOfAD pathology." (PMID 30150923, 2018). "Processing of the Alzheimer disease (AD) associated amyloid-β (Aβ) precursor protein (APP) is mediated by at least three different proteases." (PMID 28323844, 2017). "Alzheimer’s disease is postulated to be caused by the formation of senile plaques from the Aβ protein, a soluble, unstructured peptide cleaved from the membrane-embedded amyloid precursor protein (APP) by β and γ secretase enzymes to a length of 38–43 amino acid residues." (PMID 28631243, 2017). "Also, rare variants in TREM2 and APP genes were associated with Alzheimer’s disease." (PMID 28449691, 2017). "Alzheimer’s disease occurs in a sporadic form (also described as late onset Alzheimer’s disease) of unclear cause, while the familial form (known as early onset) is caused by mutations either in the Amyloid Precursor Protein (APP) gene or the APP cleaving gamma-secretase complex." (PMID 26216398, 2016). "In the present study, we tested whether the volatile metabolome was altered by mutations of the Alzheimer’s disease (AD)-implicated amyloid precursor protein gene (APP) and comprehensively examined urinary volatiles that may potentially serve as candidate biomarkers of AD." (PMID 26762470, 2016). "This phenotype is accelerated when either APP or CP is genetically ablated in mice and may be a contributory pathogenic mechanism in human diseases associated with each protein, such as Alzheimer’s disease, Parkinson’s disease or aceruloplasminemia." (PMID 25464026, 2014). "Our transformed cells could readily be propagated in culture and should provide an excellent experimental medium for elucidating aspects of the molecular pathogenesis of Alzheimer’s disease, especially those concerning the amyloidogenic pathways involving mutations in the APP coding sequence." (PMID 24223114, 2013). "Thus, defective axonal transport of APP in Alzheimer's disease may be more closely linked to defects in calsyntenin-1 rather than JIP1 mediated cargo transport." (PMID 23825109, 2013). "Aβ peptides, which deposit in the brains of patients with Alzheimer’s disease (AD), are produced by the sequential cleavage of amyloid precursor protein (APP) by β-secretase 1 (BACE1) and γ-secretase." (PMID 41558820, 2026). "Evidence from preclinical models: a study was conducted to determine the impact of aerobic exercise on the progression of Alzheimer's disease (AD) in APP/PS1 mice via the regulation of mitochondrial proteostasis." (PMID 41601887, 2026). "Amyloid precursor protein (APP) is central to Alzheimer's disease pathogenesis, yet the coordination chemistry and functional impact of core peptide fragments within its copper binding domain (CuBD) remain elusive." (PMID 41868350, 2026).
Alzheimer disease (continued). "Hyperphosphorylated collapsin response mediator protein 2 (CRMP2) is elevated in the cerebral cortex of an APP-SAA knock-in mouse model of Alzheimer’s disease and binds the adenine nucleotide translocase (ANT) in a phosphorylation-dependent manner." (PMID 41597254, 2026). "Huang and co‐workers evaluated the potential of berberine to improve cognitive dysfunction through enhancing autophagic clearance as well as inhibition of ß‐amyloid production in the APP/Tau/PS1 mouse model of Alzheimer's disease." (PMID 41020314, 2026). "The proteolytic processing of the amyloid precursor protein (APP) is a core pathological event in Alzheimer's disease (AD) pathogenesis, yet the global genetic regulatory networks modulating this process have not been fully characterized." (PMID 42123509, 2026). "Familial Alzheimer's disease patient induced pluripotent stem cells carrying mutant APP V717I and their isogenic controls were differentiated into cortical glutamatergic neurons and astrocytes using dual-SMAD inhibition followed by in vitro corticogenesis." (PMID 42117065, 2026). "Previous researches also indicated acupuncture at this acupoint improves cognitive function of APP/PS1 Alzheimer’s disease mice, modulates the brain-derived neurotrophic factor secretion in the hippocampal dentate gyrus." (PMID 41530867, 2026). "In Alzheimer’s disease, Aβ accumulation results from aberrant enzymatic cleavage of amyloid precursor protein (APP) mediated by β- and γ-secretases." (PMID 41516384, 2026). "There is compelling evidence that classical Alzheimer's disease (AD) is triggered by toxic species of Aβ, a cleavage product of amyloid precursor protein (APP)." (PMID 41549054, 2026). "Our findings indicate a disturbed glial morphology and dysfunctional TGF-β signaling cascade in the APP/PS1 model, underlining their potential role in Alzheimer's disease pathogenesis." (PMID 41750318, 2026). "During the processing and assembly of β-amyloid precursor protein (APP), the amyloidogenic pathway represents a crucial component of Alzheimer's disease (AD) pathogenesis." (PMID 41737532, 2026). "The amyloid precursor protein (APP) plays a pivotal role in the pathogenesis of Alzheimer's disease (AD)." (PMID 41277195, 2026). "Identification of APP (amyloid beta precursor protein), a cell surface receptor is intriguing, with very little known apart from its role in Alzheimer disease and amyloidosis." (PMID 40759629, 2025). "APP can be processed to generate amyloid-β, which accumulates in plaques in the brains of people who have Alzheimer’s disease and is the upstream trigger of disease." (PMID 39841661, 2025). "This pilot study investigated vascular reactivity in Alzheimer’s disease using IVM in the APP/PS1 (line 85) mouse model (Jackson Laboratories)." (PMID 39995945, 2025). "Proteolytic processing of the amyloid-beta precursor protein (APP) is a central event in Alzheimer’s disease pathogenesis." (PMID 40671818, 2025). "In Alzheimer’s disease and other tauopathies, dysregulation of these enzymes and pathways alters glycosylation homeostasis, thereby influencing APP metabolism, tau aggregation, receptor signaling, and neuroinflammation." (PMID 41462898, 2025). "Inhibition of amyloid precursor protein (APP) beta-site cleaving enzyme 1 (BACE1) has been a target for Alzheimer's disease (AD) therapeutic development." (PMID 40399225, 2025). "Differential transcript usage analysis highlighted transcript-specific changes in disease-relevant genes such as APP, KIF2A and BSCL2, associated with Alzheimer’s disease, neuronal migration disorders and degenerative axonopathies, respectively." (PMID 40735840, 2025). "The APP gene is involved in Alzheimer disease and cerebral amyloid angiopathy and the APP-AON was designed to skip exon 17 (all exon numbers mentioned refer to the MANE select transcript) as this exon contains a mutation in Dutch-type CAA." (PMID 41066632, 2025).
Alzheimer disease (continued). "Trazodone has been reported to inhibit the PERK–eIF2α signaling pathway, which is overactivated in Alzheimer’s disease and contributes to abnormal amyloid precursor protein (APP) translation and Aβ accumulation;." (PMID 41550299, 2025). "Rare genetic variants in the APP and PSEN1 and PSEN2 genes have been reported as pathogenic causes of early-onset Alzheimer’s disease, but they account for less than 1% of all cases." (PMID 39810256, 2025). "Background/Objectives: Background: Early-onset Alzheimer’s disease (EOAD) is primarily inherited in an autosomal dominant pattern, with mutations in the APP, PSEN1, and PSEN2 genes being central contributors." (PMID 40149496, 2025). "Roflumilast, in an Alzheimer’s disease (AD) model using APP/PS1 double transgenic mice, showed reduced neuronal death, increased cAMP/CREB/BDNF signaling, and improved Bcl-2/Bax ratios." (PMID 39851514, 2025). "Conversely, it phosphorylates PS1, which inhibits APP cleavage and Aβ synthesis while modulating the Aβ 42/40 ratio, hence aggravating Alzheimer's disease." (PMID 40520520, 2025). "Extracellular vesicles produced from plasma have been shown to accelerate the onset of Alzheimer’s disease in transgenic mice by cleaving substrates such as amyloid precursor protein (APP) in target neurons." (PMID 40242755, 2025). "The 3×Tg-AD mouse model, which carries three gene mutations—APP (Swedish), PS1 (M146V), and tau (P301L)—exhibits pathological features that more closely resemble those of human Alzheimer’s disease compared to other models." (PMID 40438332, 2025). "Acts as an RNA‐binding protein to stabilize APP mRNA → increases APP levels → promotes Alzheimer's disease pathology." (PMID 40904702, 2025). "In Alzheimer’s disease (AD) models (APP/PS1, 3xTg-AD, and Tg2576), early sleep problems include diminished SWS and REM sleep, increased awakenings, and circadian rhythm disruption." (PMID 40868257, 2025). "Our data therefore demonstrate physiological roles for APP in membrane-dependent protein aggregation, involving molecular mechanisms, which when disrupted by Aβ peptides, trigger Alzheimer’s disease-relevant pathologies." (PMID 40676215, 2025). "Consistent with prior reports of hippocampal hyperexcitability in Alzheimer's disease, APP/PS1 mice exhibited increased CA1 network excitation, as indicated by fE/I > 1, around 6–7 months." (PMID 41293234, 2025). "For example, modifying three specific murine codons in the amyloid precursor protein (APP) gene reconstructs the condition necessary for the development of Alzheimer’s disease." (PMID 40491567, 2025). "HDAC inhibitors have been demonstrated to improve memory retention in an Alzheimer’s disease model utilizing APP/PS1 mice." (PMID 40964091, 2025). "In experimental models of Alzheimer's disease, transplantation of in vitro cultured EPCs into APP/PS1 transgenic mice can repair the blood-brain barrier, trigger angiogenesis and decrease Aβ deposition." (PMID 40034682, 2025). "The first evidence of exosome-dependent secretion of Alzheimer’s disease-related proteins came from the localization of the enzymes responsible for cleaving the amyloid precursor protein (APP)." (PMID 40385290, 2025). "In models of Alzheimer’s disease, such as transgenic APP/PS1 mice or Aβ-injected rats, conditioned taste aversion performance is often impaired, reflecting hippocampus-dependent deficits in associative learning and aversive memory processing." (PMID 40801602, 2025). "Insertions and deletions can modify copy number which can influence disease development for a range of diseases, including Alzheimer’s disease (APP duplication), Parkinson’s disease (SNCA duplication), and various heart diseases." (PMID 40502163, 2025). "Second, we demonstrate that ERβ1 repressed the promoter activity of two genes correlated with the severity and progression of Alzheimer Disease—amyloid-beta precursor protein (APP) and inositol–trisphosphate 3–kinase B (ITPKB)." (PMID 40475329, 2025).
Alzheimer disease (continued). "Used to quantify microglial changes due to fixation or aging, as well as in studies involving microglial depletion or mouse models of Alzheimer’s disease (APP/PS1 Tg mice)." (PMID 40332469, 2025). "The mRNA levels of GSK3β and APP were significantly increased in the Alzheimer’s disease rats group compared with normal rats." (PMID 39850118, 2025). "Particularly, early-onset alzheimer disease (EOAD) is a subset of AD caused by genetic changes that affect the proteolysis and expression of APP." (PMID 40309514, 2025). "A transgenerational reduction in Alzheimer’s disease pathology was found in APP/PS1 mice offspring from a mother with a choline-enriched diet and linked to the reduction in brain homocysteine level." (PMID 40806292, 2025). "Asparagine endopeptidase (AEP) plays a critical role in Alzheimer's disease (AD) by cleaving amyloid precursor protein (APP) at N585 and tau protein at N368." (PMID 40816999, 2025). "In Alzheimer’s disease brains, APP-overexpressing mice, and neuronal cells exposed to Aβ, there is a reduction in MADD expression at both the protein and mRNA levels, accompanied by alterations in MADD splicing, which can further promote neuronal cell death." (PMID 40659647, 2025). "The deposition of toxic aggregated amyloid-β (Aβ), resulting from continuous cleavage of amyloid precursor protein (APP) by β-site APP cleaving enzyme 1 (BACE1) and γ-secretase, is a key pathogenic event in Alzheimer's disease (AD)." (PMID 40814010, 2025). "Our study demonstrates that NC treatment exerts beneficial effects on key histological, behavioral, and molecular features of Alzheimer’s disease in the APP/PS1 mouse model." (PMID 40801602, 2025). "Studies have shown dysfunctional mitochondrial distribution in neurons from Alzheimer’s disease patients and in transgenic Tg2576 mice, which express the amyloid precursor protein (APP)." (PMID 39477877, 2025). "In fact, the machine learning approach places HspB1 along with amyloid precursor protein (APP) as a biomarker for Alzheimer’s disease." (PMID 40003991, 2025). "Mass spectrometry-based proteomics identifies proteins that interact with or are modulated by the compound, including key Alzheimer’s disease targets such as tau, APP C-terminal fragments, and oxidative stress-related enzymes." (PMID 41462623, 2025). "Duplication of either the APP locus alone or other genes on chromosome 21 can contribute to Alzheimer disease development, cognitive decline, and dementia." (PMID 40333415, 2025). "This parameter is used to quantify microglial changes due to fixation or aging or in mouse models of Alzheimer’s disease (APP/PS1 Tg mice)." (PMID 40332469, 2025). "On the other hand, a study demonstrated that a supplementation of GOS or a mix of FOS and GOS decreased GABA levels in cortex of APP/PS1 Alzheimer’s disease mice." (PMID 40175389, 2025). "We and others have demonstrated the role of meprin β in the cleavage of the amyloid precursor protein (APP), a mechanism linked to the generation of amyloid‐β peptides, which are essential to the pathogenesis of Alzheimer's disease." (PMID 40396346, 2025). "In the APP/PS1 mouse model of Alzheimer’s disease, which overexpresses mutant human amyloid precursor protein (APP) and presenilin 1 (PS1) and accumulates β-amyloid, microglia display increased TLR4 expression compared with wild-type controls." (PMID 41465422, 2025). "Changes in Helicobacteraceae abundance were reported in the APPswe/PS1dE9 mouse model of Alzheimer’s disease and in 3xTg mice (expressing APP, PS1, and P301L tau) have similar results in abundance for the family taxa S24.7." (PMID 40427529, 2025). "Probably, this strategy, as well as a decrease in APP or BACE1 (which encodes β-secretase) expression, will be helpful in treating Alzheimer’s disease." (PMID 40650152, 2025).